MUC4 (mucin 4, cell surface associated)
Diseases named in the same sentence as MUC4 in open-access papers (continued):
Sharing a sentence is not in itself a finding about the gene and the disease.
myxofibrosarcoma (4 papers, 2023 to 2024). A malignant fibroblastic neoplasm arising from the soft tissue. "In terms of immunohistochemistry, low-grade myxofibrosarcoma was positive for MUC4, BCL-2, CD99, and vimentin." (PMID 37189471, 2023). "LGFM has basically no expression except MUC4 diffuse strong positive, but low-grade myxofibrosarcoma will have DDIT3 gene breakage, while LGFM has MUC4 strong positive expression and FUS-CREB3L2 fusion." (PMID 38347522, 2024). "The lack of MUC4 expression in this environment shows that it is not a significant marker for myxofibrosarcoma." (PMID 38156143, 2023). "Myxofibrosarcoma’s IHC profile is influenced by the lack of substantial MUC4 expression." (PMID 38156143, 2023).
nasal polyp (4 papers, 2018 to 2023). "Interestingly, the MUC4-GRα complex was significantly increased in patients with GCR in nasal polyps, indicating that overexpression of MUC4 may contribute to GCR development in these patients." (PMID 37986338, 2023). "Some studies investigated the pattern of expression of mucin in healthy nasal tissues and nasal polyps, which found that overexpressions of MUC1, MUC4, MUC5AC, and MUC5B are in nasal polyps than in healthy nasal tissues." (PMID 32812123, 2020). "Among the mucin family members, the expressions of MUC1, MUC2, MUC4, MUC5AC, and MUC5B have been detected in the human nasal polyp and middle ear epithelial cells." (PMID 32054887, 2020).
Barrett esophagus (3 papers, 2020 to 2023). Esophageal lesion lined with columnar metaplastic epithelium which is flat or villiform. "However, increased MUC4 has also been observed other diseased esophagus states, including Barrett's esophagus and high-grade intraepithelial neoplasia." (PMID 37692891, 2023).
breast tumor (3 papers, 2009 to 2023). "shRNA-mediated MUC4 knockdown compromised the migration, proliferation and anoikis resistance of JIMT-1 cells, strongly suggesting that MUC4 expression actively contributes to cellular properties associated with breast tumor metastasis." (PMID 19761616, 2009). "To examine patterns of MUC4 protein expression in breast tumors, we first optimized the 1G8s antibody preparation for immunohistochemical reactivity toward MUC4-expressing cultured cells." (PMID 19761616, 2009). "MUC4 expression is regained in many lymph node metastases relative to primary breast tumor, raising the possibility that the presence of MUC4 confers an advantage to metastasizing tumor cells." (PMID 19761616, 2009). "The observations described here provide strong evidence that MUC4 becomes re-expressed during the transition of primary breast tumor to metastatic lesion." (PMID 19761616, 2009). "The simplest explanation for these observations is that MUC4 expression is a marker for fully differentiated breast epithelium, and dedifferentiated breast tumor cells are impaired in their ability to support MUC4 expression." (PMID 19761616, 2009). "Collectively, the accumulated data point to a scenario where re-expression of MUC4 by a subset of primary breast tumor cells promotes their metastasis via several mechanisms." (PMID 19761616, 2009). "Moreover, it would be intriguing to correlate the expression level of Muc4 with proliferative indexes (such as Ki-67) or the expression of pro- and anti-apoptotic markers in breast tumors." (PMID 37367035, 2023). "Indeed, we further demonstrate that the presence of endogenous MUC4 in a cultured breast tumor line derived from a pleural metastasis promotes cell migration, proliferation and resistance to anoikis." (PMID 19761616, 2009). "Moreover, because only modest amounts of material were available for some samples, reflected in low actin content by immunoblotting, the figure of 84% must be considered to be a lower limit for the extent of Muc4 expression in breast tumors." (PMID 19761616, 2009). "Importantly, in both individual and paired analyses MUC4 expression was significantly higher (P < 0.05) in metastatic lesions than in primary tumors, suggesting that MUC4 re-expression may be common to breast tumor metastasis." (PMID 19761616, 2009). "An important limitation of the current study is that we did not determine Muc4 expression during breast tumor development and progression." (PMID 37367035, 2023). "The present study aimed to investigate the expression of the membrane mucin MUC4 in normal breast tissue, primary breast tumors and lymph node metastases, and to evaluate the role of MUC4 in promoting the malignant properties of breast tumor cells." (PMID 19761616, 2009). "Moreover, MUC4 knockdown limited the progression of both adherent and suspended JIMT-1 cells through the cell cycle, suggesting that MUC4 may promote the proliferation of metastasizing breast tumor cells." (PMID 19761616, 2009).
chronic bronchitis (3 papers, 2016 to 2022). A type of chronic obstructive pulmonary disease characterized by chronic inflammation in the bronchial tree that results in edema, mucus production, obstruction, and reduced airflow to and from the lung alveoli. "Recently it has been shown that chronic bronchitis and smoking are associated with the presence of MUC1 and MUC4, as well as sub-epithelial cell fibrosis and airway wall thickening." (PMID 35205621, 2022). "In conclusion, we detected an association of MUC1 and MUC4 expression with smoking and with chronic bronchitis, but not with airway obstruction." (PMID 32948202, 2020). "Female subjects with chronic bronchitis had higher levels of MUC1 and MUC4 in comparison with the subjects without chronic bronchitis." (PMID 32948202, 2020).
clear cell renal cell carcinoma (3 papers, 2017 to 2020). "Likewise, MUC4 mutations prolonged survival in renal clear cell carcinoma patients (KIRC: HR, 0.570; 95% CI 0.370–0.880; P = 0.012), an observation that is consistent with another study." (PMID 31036064, 2019). "Like KIRP, kidney clear cell carcinoma (KIRC) trends with lower rate of mucin mutations, except for MUC4, which shows a cluster of in-frame deletions for KIRC." (PMID 28978023, 2017).
colon adenocarcinoma (3 papers, 2009 to 2025). "MUC4 nonsynonymous mutations were significantly associated with reduced IgM/IgD B cells in colon adenocarcinoma (estimate = −3.7, adjusted P = 0.007)." (PMID 39966644, 2025). "A consistent fraction of these mucins is associated with diseased states, i.e., colon adenocarcinoma (MUC1, MUC2, MUC4, MUC5A/B/C), breast and uterine cancers (MUC1), and lung diseases, which may cause bronchiectasis (MUC)." (PMID 27406561, 2016).
esophageal squamous cell carcinoma (3 papers, 2020 to 2024). Esophageal squamous cell carcinoma (ESCC) is a type of esophageal carcinoma (EC) that can affect any part of the esophagus, but is usually located in the upper or middle third. "We checked the Muc4 gene mutations of human esophageal squamous cell carcinoma on the COSMIC website." (PMID 36430789, 2022).
extra hepatic bile duct carcinoma (3 papers, 2009 to 2012). "Another recent study has shown MUC4 to be a novel prognostic factor of extra-hepatic bile duct carcinoma." (PMID 21886786, 2011).
idiopathic pulmonary fibrosis (3 papers, 2016 to 2021). Idiopathic pulmonary fibrosis (IPF) is a nonneoplastic pulmonary disease that is characterized by the formation of scar tissue within the lungs in the absence of any known cause. "Mucin family members, including MUC4, play important regulatory roles in proliferation, epithelial to mesenchymal transition (EMT), fibroblast to myofibroblast transition (FMT), tissue remodeling and fibrosis as observed in diseases such as idiopathic pulmonary fibrosis (IPF) and cancer." (PMID 34262555, 2021).
leukemia (3 papers, 2013 to 2025). A malignant (clonal) hematologic disorder, involving hematopoietic stem cells and characterized by the presence of primitive or atypical myeloid or lymphoid cells in the bone marrow and the blood. "Interestingly, DHH-RHEBL1-positive patients showed higher expression of several genes known to be associated with leukemia occurrence and/or tumor progression, such as FLT3, BEX1, MUC4 and AFAP1L2." (PMID 24127550, 2013). "As expected, several previously reported genes with abnormal methylation in leukemias such as CPEB1, BLK, FLT3, ZCCHC7, EBF1, HDACs, IKZF1, RB1, CDK6, DOCK5, DPP10, MUC4, JAKs, KIT, KRAS, LINC01013, MAD1L1, NOTCH1, and STATs, among others, were also detected." (PMID 41226303, 2025).
meningioma (3 papers, 2021 to 2024). A generally slow growing tumor attached to the dura mater. "In vitro, MUC1 and MUC4 were highly expressed in the benign meningioma cell lines—SUT-MG12 and SUT-MG14—, but only MUC1 was highly expressed in the malignant meningioma cell lines—HKBMM and IOMM-Lee." (PMID 38274327, 2024). "However, the exact mechanism of MUC1 or MUC4 in the development and progression of meningioma is still unclear." (PMID 38274327, 2024). "It interacts with other ECM proteins known to be widely expressed in meningiomas such as MUC4, α5β1 integrins, laminin-α2 chain and fibronectin, to facilitate cell motility, proliferation and angiogenesis, but is not currently known to play any role in meningioma pathogenesis." (PMID 33429944, 2021). "In silico, MUC1, MUC3, MUC4, and MUC13 were highly expressed in meningiomas (GEO database series GSE16581)." (PMID 38274327, 2024). "In the GEO database, the respective mRNA expressions of MUC1, MUC3, MUC4, and MUC13 was detected in Grade I, Grade II, and Grade III meningiomas." (PMID 38274327, 2024). "In contrast, MUC1 and MUC4 were highly expressed in primary benign—SUT-MG12 and SUT-MG14—meningioma cell lines." (PMID 38274327, 2024). "Our study identified mucins like MUC1, MUC4, and MUC5A as significantly altered proteins in meningioma grade comparison." (PMID 37770851, 2023). "The analysis showed that a combination of MUC4 and MUC1 followed by SPTB2 and S100A11 showed segregation as a marker pair between low grade and high grade meningioma in tissue." (PMID 37770851, 2023). "Expression of mucins, particularly mucin 4 (MUC4), is widely expressed in meningiomas." (PMID 38274327, 2024). "However, Plectin (PLEC) and Mucins (MUC4, MUC5A, MUC1) were found to be downregulated in high grade Meningioma." (PMID 37770851, 2023).
mesenchymal neoplasm (3 papers, 2022 to 2024). "In summary, we described four extra-abdominal round cell/epithelioid mesenchymal neoplasms sharing EWSR1::ATF1 fusions, frequent expression of epithelial and neuroendocrine markers, occasional aberrant expression of ALK and MUC4, but not fitting with any currently defined mesenchymal neoplasm." (PMID 39031200, 2024).
periodontitis (3 papers, 2015 to 2022). An acute or chronic inflammatory process that affects the tissues that surround and support the teeth. "The most highly up-regulated gene associated with periodontitis was MUC4, a completely novel finding." (PMID 26686060, 2015). "MUC4 has previously been implicated in cancer, including pancreatic, breast, and lung.In reference to pathogenesis of periodontitis, studies have reported higher levels of mucins in general in saliva samples from periodontitis patients than in healthy subjects." (PMID 36518149, 2022). "Mucin 4 (MUC4) and matrix metalloproteinase 7 (MMP7) have been reported to be associated with chronic periodontitis as seen in gingival tissue biopsies." (PMID 36518149, 2022). "The results revealed that periodontitis contributed significantly (p < 0.05) to the levels of MUC4 in saliva samples, when adjusting for age and smoking." (PMID 36518149, 2022). "The regulation of MUC4, which was exclusively expressed in the epithelium of gingival tissue of patients with periodontitis, was studied in gingival epithelial cells." (PMID 26686060, 2015). "The two most up-regulated genes in connection with periodontitis, MUC4 and MMP7, were investigated further." (PMID 26686060, 2015). "The present RNA-seq study of the global transcriptome of periodontitis identified MUC4 and MMP7 as the two most highly up-regulated genes in periodontitis." (PMID 26686060, 2015). "The MUC4 protein was detected in the gingival epithelial cells of 18 (90%) patients with periodontitis but only 2 (10%) of the healthy control subjects (P < 0.001)." (PMID 26686060, 2015). "The most highly up-regulated gene was mucin 4 (MUC4), and its protein product was confirmed to be over-expressed in periodontitis." (PMID 26686060, 2015). "At the mRNA level, our previous sequencing study, investigating the whole transcriptome in gingivaltissue biopsies from periodontitis patients and healthy controls, identified higher expression of MUC4 in gingival tissue biopsies from patients with periodontitis." (PMID 36518149, 2022). "This suggests that MUC4 and MMP7 combination are diagnostic markers for periodontitis." (PMID 36518149, 2022). "The overexpression of MUC4 in the epithelial gingival tissue of patients with periodontitis suggests that this protein might also be present at elevated levels in saliva and GCF, providing non-invasive diagnostic markers for early detection and monitoring of the progression of periodontitis." (PMID 26686060, 2015). "MUC4 levels were significantly lower in saliva and GCF from periodontitis patients compared to healthy controls." (PMID 36518149, 2022). "We report significantly varied levels of MUC4 and MMP7 in saliva and GCF of patients with periodontitis in comparison to healthy controls." (PMID 36518149, 2022). "The reduced levels of MUC4 in saliva might lead to their lower capability to agglutinate as well as cleanse oralpathogens or antigens, allowing biofilm formation on the tooth surface, leading to subclinical constant inflammatory response in periodontitis patients." (PMID 36518149, 2022). "The top two most up-regulated genes were MUC4 and MMP7, and the corresponding proteins of these genes were also overexpressed in gingival tissue from patients with periodontitis." (PMID 26686060, 2015). "Our novel findings suggest MUC4 and MMP7 to be potential biomarkers and therapeutic targets for periodontitis." (PMID 26686060, 2015). "Therefore, it is of interest to estimate the levels of MUC4 and MMP7 in saliva and gingivalcrevicular fluid (GCF) samples of periodontitis in adolescents patients at West Bengal, India." (PMID 36518149, 2022). "In addition to saliva samples, the levels of MUC4 and MMP7 were also investigated in GCF samples from a cohort of 40 subjects with periodontitis and healthy controls." (PMID 36518149, 2022). "Thus, studies are ongoing to investigate the levels of MUC4 in saliva and GCF in a large cohort of patients with periodontitis and healthy controls." (PMID 26686060, 2015).
periodontitis (continued). "Thus, MUC4 and MMP7 are biomarkers for periodontitis diagnosis and towards further consideration." (PMID 36518149, 2022). "Furthermore, in this studygroup, combination of the salivary levels of MUC4 and MMP7 is also demonstrated that has shown the potential of discriminating between individuals with and without periodontitis." (PMID 36518149, 2022).
squamous cell carcinoma (3 papers, 2014 to 2025). A carcinoma arising from squamous epithelial cells. "Further, different glycoforms of MUC4 were observed in squamous cell carcinoma cell line in comparison to TCC cell lines." (PMID 24671186, 2014). "Also, we found positive immunoreactivity for MUC4 in some cases of adenocarcinoma and squamous cell carcinoma with no CEA and/or Claudin 4 expression." (PMID 29317712, 2018). "No significant co-relation could be assessed between MUC4 expression and grade of squamous cell carcinoma due to limited information on tumor grade of cases." (PMID 24671186, 2014).
synovial sarcoma (3 papers, 2016 to 2023). "MUC4 was shown to be highly expressed in SEF (n=13) and LGFMS (n=10), while focal positivity in synovial sarcoma (n=1)." (PMID 38156143, 2023). "While MUC4 is not usually thought of as a key marker for synovial sarcoma, localized positivity implies that it is expressed in certain instances." (PMID 38156143, 2023). "They reported that all 49 LGFMS cases (100%) showed cytoplasmic staining for MUC4 and all other tumor types were negative for MUC4, other than 6 (30%) monophasic synovial sarcomas." (PMID 27247823, 2016).
viral infection (3 papers, 2020 to 2024). "The importance of Muc4 was also determined during pathology of the mosquito-borne Chikungunya virus, possibly indicating a broader importance of Muc4 during viral infection." (PMID 33184103, 2020). "In addition, in chikungunya virus (CHIKV) infection, the loss of MUC4 also results in augmented disease during early time points, indicating a possible broad role for MUC4 in viral infection and pathogenesis." (PMID 34064525, 2021).
acute myeloid leukemia (2 papers, 2018 to 2021). Acute myeloid leukemia (AML) is a group of neoplasms arising from precursor cells committed to the myeloid cell-line differentiation. "(B) Overall survival of MUC4/MUC16/MUC20 high and low risk group in liver and acute myeloid leukemia (AML)." (PMID 30236127, 2018).
astrocytoma (2 papers, 2020 to 2022). "Interestingly, we also found MUC4, which encodes a cell surface associated protein involved in repression of apoptosis and stimulation of proliferation, to be affected by SNVs in more than 50% of astrocytomas." (PMID 32604718, 2020). "Still, additional experimental studies are necessary to further evaluate the role of MUC4 in astrocytoma progression and its potential clinical utility." (PMID 32604718, 2020). "In addition, MUC4 expression levels in astrocytomas were comparable to those of the normal brain references." (PMID 32604718, 2020). "Interestingly, different studies have already reported the importance of MUC4 in different cancer types including astrocytomas." (PMID 32604718, 2020). "Thus, all these different studies indicate that MUC4 could also play an important role in astrocytoma progression." (PMID 32604718, 2020). "Furthermore, within the different major astrocytoma progression groups, we did not observe MUC4 expression changes for A2 to G4 and A3 to G4, but there was a tendency of reduced MUC4 expression levels for A2 to A3 patient-matched pairs." (PMID 32604718, 2020).
cervical squamous cell carcinoma (2 papers, 2015 to 2018). A squamous cell carcinoma arising from the cervical epithelium. "It has been reported that the MUC family genes, MUC1, MUC16 and MUC4, are upregulated in cervical squamous cell carcinoma." (PMID 25789025, 2015).
colorectal adenocarcinoma (2 papers, 2023). The most common type of colorectal carcinoma. "In support of this finding, MUC4 was also associated with DSS in the “colorectal adenocarcinoma TCGA PanCancer Atlas” dataset." (PMID 36675796, 2023).
colorectal tumors (2 papers, 2022 to 2023). "In orthotopic mouse models of CRC, MUC4 conjugated to a near-infrared dye (IR800) effectively targeted and labeled primary colorectal tumors and liver metastasis." (PMID 36900282, 2023).
cyst (2 papers, 2018 to 2020). A sac-like closed membranous structure that may be empty or contain fluid or amorphous material. "Histologic and cyst fluid biomarkers for high-risk IPMN, including KRAS, GNAS, and MUC1/MUC2/MUC4/MUC5A, will be used in future decision making about treatment." (PMID 33145018, 2020). "The result showed that mucinous cystic neoplasms and serous cystadenoma cysts, combined, were 18 times more likely to express MUC4 protein than the pseudo cyst and the not otherwise specified cysts (p=0.022)." (PMID 34164227, 2018).
diabetes (2 papers, 2021 to 2023). "The effects of four MUC4 polymorphisms (rs882605 G>T, rs1104760 A>G, rs2688513 A>G, and rs2246901 A>C) on CRC risk were evaluated and age, sex, hypertension, diabetes mellitus, body mass index (BMI), and high-density lipoprotein cholesterol (HDL-C) levels were adjusted." (PMID 37384668, 2023).